MMP8 (matrix metallopeptidase 8)
Diseases named in the same sentence as MMP8 in open-access papers (continued):
Sharing a sentence is not in itself a finding about the gene and the disease.
periodontitis (continued). "Nonetheless, there was a trend towards increased concentration of MMP-8 in the chronic periodontitis groups (DM + CP and CP) compared to the DM group." (PMID 26989414, 2016). "The results based on 2,724 periodontitis patients and 3,438 controls showed that MMP-9-1562C/T, MMP-3-1171 A5/A6, and MMP-8-799C/T polymorphisms were associated with periodontitis susceptibility." (PMID 27095260, 2016). "In the present meta-analysis, we aggregated data from published studies to estimate genetic associations between MMP gene, namely MMP-2-753 C/T, MMP-3-1171 A5/A6, MMP-8-799 C/T, and MMP-9-1562 C/T polymorphisms, and periodontitis susceptibility." (PMID 27095260, 2016). "Much greater levels of MMP-8 in GCF have been observed in periodontitis patients than in healthy subjects." (PMID 28074077, 2016). "According to previous studies, salivary MMP-8 levels are higher in coronary artery disease patients and periodontitis patients." (PMID 26132583, 2015). "For example, significantly higher levels of salivary MMP-8 in periodontitis than in healthy controls were observed in six studies that used the non-stimulatory whole saliva samples and in five studies that used stimulated whole saliva samples." (PMID 26389079, 2015). "In this report, we use a selective voting ensemble classification approach (SVA) in conjunction with a battery of classification techniques and salivary biomarkers (IL-1ß, IL-6, MIP-1α, MMP-8) to discern clinically-labeled gingivitis and periodontitis groups." (PMID 26407063, 2015). "MMP-8 (neutrophil collagenase) is increased at sites of inflammation in both GCF and saliva in periodontitis and has been suggested as a potential diagnostic molecule for the disease." (PMID 26407063, 2015). "They reported the application of the LOC system for the multiplex measurement of three salivary biomarkers, C-reactive protein, MMP-8, and IL-1β, which are related to the clinical expression of periodontitis." (PMID 26389079, 2015). "That neutrophil collagenase (MMP-8) activity in saliva is elevated in periodontitis patients as compared to healthy volunteers and it correlates with clinical measures of periodontitis is well-established by the results of numerous studies." (PMID 24944840, 2014). "The finding that subantimicrobial disease of the doxycycline inhibits MMP-8 and can be successfully used as an adjunct therapy for periodontitis further endorses the importance of MMP-8 in periodontitis." (PMID 24944840, 2014). "Periodontitis improved in both groups in parallel with a significant reduction in salivary MMP-8 levels." (PMID 24944840, 2014). "The ability of IFMA to detect both PMN-type and fibroblast-type MMP-8 and especially in their active forms, explains its strength in differentiating periodontitis and healthy subjects." (PMID 26464855, 2014). "In this regard, MMP-8 seems to be a better biomarker of periodontitis than other markers such as IL-1β." (PMID 24944840, 2014). "In periodontitis, it has been proposed that the relationship between ROS and MMPs is bidirectional; the increase in ROS activates latent MMPs, specifically collagenase MMP-8 and gelatinase MMP-9, which are directly responsible for collagen breakdown." (PMID 41590173, 2026). "However, in patients with periodontitis, even after successful therapy, the amount of MMP-8 in the pocket remains higher compared to healthy subjects." (PMID 41440646, 2025). "Similarly, reported that in saliva, the dual combinations of IL‐1β, IL‐6 and MMP‐8 have an excellent ability to detect periodontitis and a good capacity to detect non‐periodontitis, but a meta‐analysis of gingival crevicular fluid biomarkers was not possible." (PMID 39801446, 2025). "Previous research has established active MMP-8 (aMMP-8) as a reliable indicator for both peri-implant and periodontal diseases, with low aMMP-8 levels typically indicating a healthy state in cases of periodontitis." (PMID 39941195, 2025).
periodontitis (continued). "Among these biomarkers, MMP-8 and MMP-9 are proteins that cause tissue breakdown in periodontitis." (PMID 40545647, 2025). "Interestingly, while the removal of indicated studies from both biomarker cohorts slightly increased the effect size of aMMP8 in periodontitis, a drastic and opposite effect was observed in MMP8 studies." (PMID 40045958, 2025). "Notably, MMP-8, a key mediator of tissue destruction in periodontitis, is a shared biomarker between periodontitis and OSCC." (PMID 41296437, 2025). "Results aMMP-8, but not total MMP-8 or other biomarkers, associated significantly with the stage and grade of periodontitis combined (p < 0.001, Kruskal–Wallis test)." (PMID 39353614, 2025). "Additionally, elevated salivary MMP-8 levels have been reported in patients with periodontitis, showing significant correlations with clinical disease parameters." (PMID 41154468, 2025). "Matrix metalloproteinases (MMP)-8 and −9 are regarded as biomarkers for periodontitis." (PMID 40545647, 2025). "Non-invasive method of testing ISM1, MMP-8 and asprosin could be an effective reference tool for evaluating periodontitis in patients with obesity." (PMID 41063065, 2025). "Moreover, serum and GCF MMP-8 levels were higher in gingivitis and periodontitis than in healthy populations." (PMID 39641024, 2024). "MMP-8 is the major collagenolytic protease present in both gingival crevicular fluid (GCF) and gingival tissue and is implicated in the inflammatory and immunological cascades in periodontitis." (PMID 38786309, 2024). "Also in saliva, higher concentrations of MMP-8 are found in patients with periodontitis compared to healthy individuals." (PMID 38473967, 2024). "Additionally, the salivary MMP-8 levels were compared between patients with gingivitis and periodontitis." (PMID 39641024, 2024). "Elevated concentrations of MMP-8 in individuals with chronic periodontitis." (PMID 38420070, 2024). "Additionally, we found higher MMP-8 levels in periodontitis compared to gingivitis (MD = 112.04 ng/ml, CI: 56.15; 167.92)." (PMID 39641024, 2024). "Only one study included in our meta-analysis applied both ELISA (tMMP-8) and IFMA (aMMP-8) methods and reaffirmed that both methods can distinguish periodontal health, gingivitis and periodontitis based on saliva MMP-8 results; however, IFMA can detect changes in periodontal therapy as well." (PMID 39641024, 2024). "Some studies indicate that these enzymes can be considered as potential markers in the diagnosis of periodontitis and the prognosis of its development, and of particular interest in the field of periodontology is metalloproteinase 8 (MMP-8), which belongs to the group of collagenases." (PMID 38473967, 2024). "First, matrix metalloproteinase-8 (MMP-8) can be found in saliva and GCF and might be used as a diagnostic tool for monitoring periodontitis and peri-implantitis, particularly at the individual and site levels, respectively." (PMID 39795606, 2024). "The active form of MMP-8 (aMMP-8) is elevated in a diseased mouth rinse, gingival crevicular fluid, and peri-implant sulcular fluid samples and is potentially useful to diagnose, predict the stage and grade periodontitis/periimplantitis." (PMID 38786309, 2024). "As a result, MMP-8 has been suggested as a biomarker for early periodontitis diagnosis." (PMID 38535279, 2024). "Levels of aMMP-8 can be influenced by microbial proteases, such as those released by Td, which trigger specific release of neutrophils in the gingiva affected by chronic periodontitis (CP), as well as by the direct action of Td-dentilisin, activating MMP-8 to aMMP-8." (PMID 38786309, 2024). "In addition, total MMP-8 can fail or at least is clearly less efficient in periodontitis and peri-implantitis oral fluid diagnostics biomarker and treatment monitoring." (PMID 39273368, 2024).
periodontitis (continued). "Importantly, salivary MMP-8 concentrations were higher in patients with more advanced periodontitis, and Receiver Operating Characteristic (ROC) curve analysis showed that this enzyme has high diagnostic power in detecting periodontitis." (PMID 38473967, 2024). "To answer this question, we conducted an analysis to ascertain whether there are significant differences in the salivary MMP-8 levels among periodontitis, gingivitis and healthy cases." (PMID 39641024, 2024). "The levels of MMP-8 and IL-6 in GCF have shown significant potential to identify individuals with periodontitis and reflect its severity, exhibiting ROC values of 0.92 and 0.93 for MMP-8 and IL-6, respectively, distinguishing between healthy and periodontitis patients." (PMID 38802345, 2024). "Moreover, the elevated concentrations of MMP‐8 in saliva unambiguously indicate the presence of active periodontitis in individuals with diabetes." (PMID 38433295, 2024). "This contrasts with total MMP-8, which lacks precision as a biomarker for periodontitis." (PMID 38786309, 2024). "Such a modern tool may be MMP-8, an enzyme whose elevated concentrations are observed both in the gingival fluid and saliva of patients with periodontitis." (PMID 38473967, 2024). "In addition, the study provides a brief introduction on the etiology of periodontitis and the biological role of metalloproteinases and MMP-8." (PMID 38473967, 2024). "MMP-8, also referred to as collagenase-2, is the primary collagenase in the gingival connective tissue in periodontitis cases and accounts for 90–95 % of the collagenolytic activity in gingival crevicular fluid (GCF), highlighting its critical role as an indicator of periodontitis [11,12,]." (PMID 39641024, 2024). "This strip simultaneously detects three periodontitis biomarkers: MMP-8, IL-1β, and TNF-α." (PMID 39554809, 2024). "In this study, we aimed to (i) detect Td-dentilisin and MMP-8 immunoexpression levels in gingival tissue samples of patients with periodontitis compared with periodontally healthy gingivae to (ii) assess the MMP-8, MMP-2, MMP-7, TIMP-1, and IL-1β mRNA expressions in the diseased vs. healthy gingiva." (PMID 38786309, 2024). "It is suggested that in future studies, the clinical effects of MMP‐8 reduction or increase on periodontitis can be examined by examining periodontal indices, and also the role of MMP‐8 specific drugs or antagonists on periodontal disease and blood sugar control be studied." (PMID 38433295, 2024). "And the MMP‐8 is a crucial proinflammatory enzyme that is present in the IMEs of periodontitis." (PMID 37985923, 2024). "Our present ex vivo MMP-8 mRNA transcriptomic findings support and further extend those previous in vivo rather than the in vitro studies revealing rather low de novo transcriptional expression of MMP-8 RNA in the periodontitis-affected gingiva vs. healthy gingiva." (PMID 38786309, 2024). "Saliva MMP-8 level measurement is a rapid, easy, non-invasive method for diagnosing periodontitis." (PMID 39641024, 2024). "Importantly, in addition to the elevated levels of MMP-8 in periodontal patients, the levels of this enzyme correlated with some clinical parameters of periodontitis." (PMID 38473967, 2024). "Moreover, our analysis confirmed that the MMP-8 level is significantly different in gingivitis compared to periodontal health or periodontitis." (PMID 39641024, 2024). "Also, MPO, a pro-oxidative activator of MMP-8, was recorded in this study to be an efficient biomarker of periodontitis." (PMID 39273368, 2024). "They used aMMP-8 PoC mouthrinse testing and found healthy participants had significantly lower MMP-8 levels than patients with severe periodontitis; accordingly they recommended integrating aMMP-8 PoC/chair-side mouthrinse testing into the new classification system in periodontology." (PMID 39641024, 2024). "The active MMP-8 POCT identifies this periodontitis tissue destruction cascade in 5 min." (PMID 39273368, 2024).
periodontitis (continued). "Hence, MMP‐8 is regarded as a highly prospective biomarker in oral fluids for the detection of periodontitis." (PMID 38433295, 2024). "This study aimed to compare several potential mouthrinse biomarkers for periodontitis including active matrix-metalloproteinase-8 (aMMP-8), total MMP-8, and other inflammatory biomarkers in diagnosing and monitoring the effects of nonsurgical periodontal therapy." (PMID 39273368, 2024). "Therefore, MMP-8 is currently considered as one of the important biomarkers of periodontal inflammation and periodontitis." (PMID 37794378, 2023). "We have not performed additional post hoc analysis that would consider age and periodontitis as confounding factors, but it can be speculated if periodontitis prevalence and severity would have modifying effects on MMP‐8 turnover and processing in oral fluids." (PMID 37877535, 2023). "In all periodontitis groups, the salivary levels of MMP-8 determined through ELISA technique revealed a significant increase (p < 0.05) in phase 2, after the induction of periodontal disease (6.078 ng/mL, SD ± 1.684), compared with phase 1 (4.293 ng/mL, SD ± 0.788)." (PMID 36840029, 2023). "Biomarkers such as MMP-8 can assist in both staging and grading periodontitis." (PMID 37371608, 2023). "The mean value of MMP8 in the DS group with chronic periodontitis was -18.1895, which was statistically significant (P<.001) compared to the mean value of -20.3720 in systemically healthy subjects with chronic periodontitis and -21.7120 in systemically healthy controls." (PMID 37448427, 2023). "Another study also showed that cassava leaf extract could reduce MMP-8 expression in rats with ovarian dysfunction with P. gingivalis-induced periodontitis." (PMID 37293131, 2023). "Besides MMP-8, decreased levels in gingival crevicular fluids after the effective treatment of periodontitis have also been observed for MMP-1, -9, -12, and -13." (PMID 37371608, 2023). "Interestingly, the RANKL/OPG ratio and the MMP-8 levels were lower at all the analyzed time-points of the orthodontic treatment compared to those detected during periodontitis." (PMID 36902236, 2023). "In this mini-review, we aim to summarize the literature information about the functions of MMPs, paying more attention to MMP-8 (collagenase-2 or neutrophil collagenase) in the development and progression of periodontitis, peri-implantitis, and carious lesions." (PMID 37371608, 2023). "Moreover, some promising biomarkers of periodontitis were suggested, such as matrix metalloproteinase-8 (MMP-8), matrix metalloproteinase-9 (MMP-9), interleukin 1 beta (IL1β), and interleukin 6 (IL6)." (PMID 37535199, 2023). "In contrast, total MMP-8 (ELISA, enzyme-linked immunosorbent assay) has not been able, to the authors knowledge, to differentiate different stages of periodontitis, whereas aMMP-8 has." (PMID 38001886, 2023). "The mean value of MMP8 in the DS group with chronic periodontitis is -18.1895, which is statistically significant (p<.001) compared to the mean value of -20.3720 in systemically healthy subjects with chronic periodontitis and the mean value of -21.7120 in systemically healthy controls." (PMID 37448427, 2023). "During periodontitis, the MMP-8 levels detected in the vestibular periodontal sites (2755.10 pg/mL) were significantly higher than those detected in the palatine (2066.31 pg/mL, p < 0.001), distal (2197.26 pg/mL, p < 0.001), and mesial (2207.06 pg/mL, p < 0.001) sites." (PMID 36902236, 2023). "Our findings suggest that increased MMP8 and MMP9 in DS periodontitis patients could contribute to their heightened susceptibility to periodontal disease." (PMID 37448427, 2023). "Of the studies included in this systematic review, four studies evaluated the levels of the pro-inflammatory cytokines IL-1β, IL-6, and TNF-α, the anti-inflammatory cytokine IL-10, and the matrix metalloproteinase-8 (MMP8), which is associated with the clinical manifestation of periodontitis." (PMID 37109642, 2023).
periodontitis (continued). "The primary MMPs of chronic periodontitis are MMP-8 and MMP-9." (PMID 35408573, 2022). "As MMP‐8 is centrally involved in the pathogenesis of periodontitis, we aimed to evaluate the presence of genetic polymorphisms of S100A8/A9/A12, MMP8, and CFH in periodontitis." (PMID 35315933, 2022). "However, saliva levels of S100A8, S100A12, MMP‐8, and TCC, and CFH polymorphisms were associated with clinical and radiographic signs of periodontitis." (PMID 35315933, 2022). "MMP‐8 is released by polymorphonuclear leukocytes in its inactive latent proform, which is, however, converted to an active form during the progressive phase of periodontitis." (PMID 35676762, 2022). "Previously, MMP-8 and IL-6 were identified as salivary biomarkers that increased in periodontitis." (PMID 35268009, 2022). "MMP-8 is another metalloproteinase involved in the pathogenesis of periodontitis." (PMID 35454140, 2022). "Among MMP members, MMP-8 and MMP-9 were found to be elevated in the blood of patients with type 2 diabetes and metabolic syndrome, and higher concentrations of MMP-8 and−9 have been reported in the gingival tissues and oral fluids of diabetic patients with periodontitis." (PMID 35757444, 2022). "Therefore, a chairside MMP-8 test would be advisable to effectively differentiate clinically healthy sites and gingivitis from chronic periodontitis and also to effectively monitor the treatment of patients with chronic periodontitis." (PMID 35163727, 2022). "MMP-8 level is increased proportionally with the severity of periodontitis and could accurately reflect the progression and expected response to the treatment." (PMID 35270821, 2022). "Interestingly, when using ratios, the diagnostic potential increased with MMP-8/TIMP-1 (AUC of 0.986, p value = 0.0001) and MMP-9/TIMP-1 (AUC of 1.000, p value = 0.0001) between periodontal health and periodontitis." (PMID 36292174, 2022). "The reduction of MMP-8 was shown to reduce periodontitis and peri-implantitis." (PMID 35757444, 2022). "Accordingly, in the present study, we aimed to compare the diagnostic utility of the SAW biosensor with other antibody‐based assays (IFMA to measure aMMP‐8 and ELISA to measure total MMP‐8 [tMMP‐8]) in subjects with periodontal health, gingivitis, and periodontitis before and after treatment." (PMID 35304757, 2022). "However, in the periodontitis group, MMP‐8 assayed using the SAW biosensor significantly correlated with total MMP‐8 measured by ELISA (ng/ml; r = .450, p < .001) but not with aMMP‐8 measured by IFMA (ng/ml)." (PMID 35304757, 2022). "In the present study, measurements using both the IFMA and biosensor assays demonstrated significant differences in salivary MMP‐8 levels in periodontitis patients before, and 6 months after, treatment, although the statistical significance was greater with the IFMA assay." (PMID 35304757, 2022). "Considering that gingival tissues-derived MMP-3 contributes to the progression of adult periodontitis by activating MMP-8 and MMP-9 derived from crevicular fluid neutrophil, increased expression of MMPs would be responsible for age-related periodontal inflammation." (PMID 33477537, 2021). "It is noteworthy, that especially aMMP‐8 but not total or latent MMP‐8 has been implicated as a successful biomarker for periodontitis." (PMID 34448550, 2021). "Similarly, (t) MMP-8 showed higher levels in periodontitis versus healthy sites (60.62 (68.09 ng/mL) and 21.54 (37.20 ng/mL), respectively) (p < 0.001)." (PMID 34441437, 2021). "In addition, polymorphisms in MMP-1, MMP-3, MMP-8, and MMP-9 are associated with chronic periodontitis susceptibility." (PMID 33477537, 2021). "About that, the role of salivary matrix metalloproteinase (MMP-8) in relation to diabetes and periodontitis has been thoroughly investigated, and, in general terms, poor metabolic control is associated with increased salivary as well as circulating MMP-8 levels." (PMID 34054959, 2021).